SNORD114-30 (small nucleolar RNA, C/D box 114-30)
Synonyms: 14q(II-30)
Gene: Small nucleolar RNA gene on chromosome 14 (100,991,919 to 100,991,990, forward strand). Ensembl gene ENSG00000201318.
Gene Ontology:
Biological process: RNA processing
Cellular component: nucleolus
Homologues: Orthologues: chimpanzee SNORD114-30 (97% identical), macaque SNORD114-30 (93% identical), mouse DQ267101 (68% identical), mouse Gm25224 (67% identical), rat LOC120093410 (67% identical), rat LOC120097213 (67% identical), mouse DQ267102 (65% identical), rat LOC120097675 (65% identical), rat LOC120097972 (65% identical), mouse DQ267100 (64% identical), mouse Gm26922 (64% identical), rat LOC120093406 (64% identical), and 21 more. Paralogues in human: SNORD114-23 (81% identical), SNORD114-20 (79% identical), SNORD114-29 (78% identical), SNORD114-25 (76% identical), SNORD114-9 (76% identical), SNORD114-21 (75% identical), SNORD114-27 (75% identical), SNORD114-28 (75% identical), SNORD114-11 (74% identical), SNORD114-22 (74% identical), SNORD114-26 (74% identical), SNORD114-3 (74% identical), and 26 more.